RIPK4 (receptor interacting serine/threonine kinase 4)
Diseases named in the same sentence as RIPK4 in open-access papers (continued):
Sharing a sentence is not in itself a finding about the gene and the disease.
chronic cervicitis (1 paper, 2015). Chronic inflammation of the cervix. "The results revealed that RIPK4 was the optimal biomarker (YI = 71.7) for distinguishing HSIL from LSIL/chronic cervicitis relative to p16INK4a (YI = 58.4) and Ki-67 (YI = 52.4)." (PMID 26148476, 2015). "The specificity of RIPK4 for distinguishing HSIL from chronic cervicitis/LSIL was higher than that of p16INK4a (86.6% vs. 66.3%), but RIPK4 had slightly less sensitivity than p16INK4a (85.1% vs. 92.1%)." (PMID 26148476, 2015). "RIPK4 staining was found in most HSIL and CSCC cases, but RIPK4 staining appeared less in LSILs and chronic cervicitis." (PMID 26148476, 2015). "RIPK4 expression increased significantly with disease progression from 3.2% in chronic cervicitis, 19.3% in LSILs and 85.1% in HSILs to 94.4% in CSCCs (P < 0.001)." (PMID 26148476, 2015). "Therefore, the presence of HR HPV infection in chronic cervicitis and SILs with RIPK4-positive or RIPK4-negative staining requires further study in the future." (PMID 26148476, 2015). "Therefore, we analyzed RIPK4 and the traditionally reported biomarkers, p16INK4a and Ki-67, in chronic cervicitis, LSIL and HSIL." (PMID 26148476, 2015). "Interestingly, we observed RIPK4 positive expression in most HSILs and SCC, whereas only 19.3% of the LSILs and 3.2% of chronic cervicitis were RIPK4 positive." (PMID 26148476, 2015). "We next evaluated the expression of RIPK4 protein and its subcellular localization in 198 cases of CSCC, 109 cases of LSIL, 141 cases of HSIL and 63 cases of chronic cervicitis using IHC." (PMID 26148476, 2015). "We further determined the diagnostic value (sensitivity, specificity and Youden’s index (YI)) of RIPK4, p16INK4a and Ki-67 for distinguishing HISL from chronic cervicitis/LSIL." (PMID 26148476, 2015). "Moreover, RIPK4 may serve as a useful biomarker to distinguish HSIL from chronic cervicitis/LSIL, which are two different clinical types for therapeutic procedures, with a high sensitivity and specificity (85.1% and 86.6%, respectively) and the performance improved when combined with p16INK4a." (PMID 26148476, 2015). "We further analyzed the sensitivity, specificity and YI of RIPK4, p16INK4a and Ki-67 for the diagnosis of HSIL versus chronic cervicitis/LSIL." (PMID 26148476, 2015).
colon adenocarcinoma (1 paper, 2022). "RIPK4 can function as an independent prognostic indicator of worse outcome in colon adenocarcinoma (COAD) and in ovarian serous cystadenocarcinoma (OV) while RIPK4 overexpression predicts better outcome in kidney renal papillary cell carcinoma (KIRP) and kidney renal clear cell carcinoma (KIRC)." (PMID 35186499, 2022).
embryonal carcinoma (1 paper, 2023). A non-seminomatous malignant germ cell tumor characterized by the presence of large germ cells with abundant cytoplasm resembling epithelial cells, geographic necrosis, high mitotic activity, and pseudoglandular and pseudopapillary structures formation. "Tumor growth of Wnt signaling-dependent embryonal carcinoma tumor cells was inhibited by knockdown of RIPK4 in xenograft experiments, indicating an oncogenic role of RIPK4 in certain tumor types." (PMID 37688617, 2023).
head and neck squamous cell carcinoma (1 paper, 2023). A squamous cell carcinoma that arises from any of the following anatomic sites: lip and oral cavity, nasal cavity, paranasal sinuses, pharynx, larynx, and salivary glands. "In addition, ourselves and others have previously shown that RIPK4 is a NOTCH target gene that suppresses the development of cutaneous and head and neck squamous cell carcinomas (HNSCCs)." (PMID 36765696, 2023).
hearts defects (1 paper, 2024). "However, a study of DS individuals found that congenital hearts defects were associated with two short copy number variants located between RIPK4 and PRDM15 and within ZBTB21 respectively, implicating this region in DS-CHD." (PMID 38266108, 2024).
leukemia (1 paper, 2010). A malignant (clonal) hematologic disorder, involving hematopoietic stem cells and characterized by the presence of primitive or atypical myeloid or lymphoid cells in the bone marrow and the blood. "The application on a dataset of leukemia patients identifies eQTLs in the regions of the GART, PCP4, DSCAM, and RIPK4 genes that regulate ADAMTS1, a known leukemia correlate." (PMID 21044360, 2010).
liver cancer (1 paper, 2021). An epithelial or non-epithelial malignant neoplasm that arises from the liver. "Our results indicate that RIPK4 plays an important role in inhibiting the invasion and metastasis of liver cancer." (PMID 34222329, 2021).
ovarian tumor (1 paper, 2021). "The expression of RIPK4 in ovarian tumor tissues was considerably higher than that in normal ovarian tissues." (PMID 34124253, 2021). "The present study indicated that RIPK4 expression in ovarian tumor tissues based on TCGA database RNA sequencing data was remarkably higher than in normal ovarian tissues with reference to data obtained from the GTEx database using bioinformatic analysis." (PMID 34124253, 2021). "Previous studies have revealed that the expression of RIPK4 in ovarian tumor tissues is higher than that of noncancerous ovarian tissues." (PMID 34124253, 2021).
papilloma (1 paper, 2023). A benign epithelial neoplasm that projects above the surrounding epithelial surface and consists of villous or arborescent outgrowths of fibrovascular stroma. "In stark contrast, all animals infected with the sgRNA library targeting Ripk4 target genes, developed multiple papilloma and SCCs on the skin and oral cavity, indicating the existence of tumor suppressor genes within this library." (PMID 36765696, 2023). "As we have previously shown, genetic ablation of Ripk4 is sufficient to induce papilloma formation in about 60% of mice starting at 1 year of age." (PMID 36765696, 2023).
serous carcinoma (1 paper, 2021). "The results verified that the higher expression of RIPK4 was related to the type of ovarian histology, and the expression in serous carcinoma tissues was significantly higher than that in ovarian serous cystadenoma (P < 0.001)." (PMID 33855091, 2021).
serous ovarian cancer (1 paper, 2021). "The relationship between RIPK4 expression and histological type and age of enrolled benign and malignant serous ovarian tumours, as well as histological grade, lymph node metastasis, and clinical stage of serous ovarian cancer was further studied." (PMID 33855091, 2021).
testicular germ cell tumours (1 paper, 2021). "Notably, a high level of RIPK4 expression was also detected in three common gynaecological cancers and in testicular germ cell tumours." (PMID 33855091, 2021).
triple-negative breast carcinoma (1 paper, 2024). An invasive breast carcinoma which is negative for expression of estrogen receptor (ER), progesterone receptor (PR), and human epidermal growth factor receptor 2 (HER2). "This study highlights the significance of arm-level somatic copy number alterations in triple-negative breast cancer and identifies RIPK4 as a potential driver gene associated with poor overall survival and metastasis." (PMID 38744952, 2024). "RIPK4 enhanced the survival of triple-negative breast cancer cells at secondary sites, thereby facilitating the formation of metastatic lesions." (PMID 38744952, 2024).
tumor (38 papers, 2015 to 2026). "Receptor-interacting protein kinase 4 (RIPK4) has been implicated in the progression of numerous tumours." (PMID 41660747, 2026). "To elucidate critical mediators of this tumor suppressive pathway, we performed transcriptional profiling of Ripk4-deficient epidermal cells followed by multiplexed in vivo CRISPR screening to identify genes with tumor suppressive capabilities." (PMID 36765696, 2023). "In vitro experiments confirmed that the high expression of RIPK4 was associated with tumor metastasis." (PMID 34124253, 2021). "In the case of OC, the expression of RIPK4 was high in tumor tissues and RIPK4 was associated with tumor growth." (PMID 34124253, 2021). "Compelling evidence highlighted the essential and specific role of RIPK4 as a tumor suppressor in epidermal keratinocytes and RIPK4 deficiency in the skin epidermis greatly impaired skin differentiation and enhanced skin carcinogenesis." (PMID 32923402, 2020). "Furthermore, RIPK4 was also associated with tumor metastasis and is involved in the regulation of the Wnt signaling pathway." (PMID 36642706, 2023). "Importantly, expression of Elovl4 drastically reduced tumor burden as well as tumor multiplicity while increasing latency of SCC formation in Ripk4-deficient, Pik3caH1047R-mutant skin." (PMID 36765696, 2023). "Next, we tested whether forced expression of Elovl4 could rescue the tumor suppression in Ripk4-deficient skin." (PMID 36765696, 2023). "In this study, we used autochthonous mouse models, where the expression of Pik3caH1047R oncogene predisposes the skin and oral cavity to tumor development, and show that not only loss of Ripk4, but also loss of its kinase substrate Irf6, triggers rapid SCC development." (PMID 36765696, 2023). "Moreover, RIPK4 is associated with tumor metastasis and implicated in the regulation of the Wnt signaling pathway." (PMID 34124253, 2021). "Increasing evidence shows that RIPK4 is inextricably linked to human diseases, especially tumours." (PMID 34222329, 2021). "Importantly, overexpression of Elovl4 suppressed tumor growth of Ripk4-deficient keratinocytes." (PMID 36765696, 2023). "Therefore, assessment of RIPK4 expression may serve as an additional tool for identifying patients who are at risk for tumor invasion or progression, and it may be a helpful predictor for proper management of individual therapy." (PMID 26148476, 2015). "A comprehensive search on PubMed revealed a growing number of articles investigating RIPK family genes, particularly RIPK1, RIPK2, RIPK3 and RIPK4, in the context of tumor research." (PMID 38164277, 2024). "Reduced expression of Ripk4 skewed the tumor immune microenvironment, marked by elevated T cells, and altered neutrophil subsets." (PMID 38744952, 2024). "Further, our in vivo experiments demonstrated that while Ripk4 knockdown resulted in a noticeable reduction in tumor burden at early time points, the surviving cancer cells exhibited distinct growth patterns." (PMID 38744952, 2024). "In functional assays, we demonstrated that targeting Ripk4 in a murine lung metastatic TNBC model significantly reduced tumor burden, improved survival, and increased CD4+ and CD8+ T cell infiltration." (PMID 38744952, 2024). "We previously observed that RIPK4 downregulation inhibits proliferation, migration, and tumor growth in WM266.4 and A375 cells." (PMID 38656555, 2024). "Despite this, the significant role of RIPK4 in modulating the tumor immune microenvironment is well established in our findings, therefore, we chose not to pursue validation using immunocompromised models." (PMID 38744952, 2024). "Depending on the cellular context, RIPK4 can act either as a tumour suppressor or a tumour promoter." (PMID 39766280, 2024). "Given the impact of RIPK4 on metastasis in our model, we further explored the functional link between tumor cell-RIPK4 and neutrophils." (PMID 38744952, 2024).
tumor (continued). "Knockdown of RIPK4 mRNA by RNAi in keratinocytes resulted in increased tumor size in xenografted transplants, supporting a tumor suppressor function for RIPK4 in skin keratinocytes." (PMID 38630705, 2024). "We have previously shown that RIPK4 is down-regulated in SCCs and functions as a tumor suppressor in skin keratinocytes." (PMID 38630705, 2024). "Several studies indicate that RIPK4 can act as both a tumor suppressor and a tumor oncogene, depending on the type of cancer." (PMID 38656555, 2024). "In vivo rescue experiments using Ripk4 or a kinase-dead Ripk4 mutant showed that the tumor suppressive function of Ripk4 is dependent on its kinase activity." (PMID 36765696, 2023). "RIPK1 and RIPK3 control and execute necroptosis in keratinocytes, as in other cell types, while RIPK4 controls proliferation and differentiation of keratinocytes and thereby can act as a tumor suppressor in skin." (PMID 37688617, 2023). "Together, these data demonstrate that Elovl4 is not only essential for tumor suppression, but also sufficient to reduce SCC development in Ripk4-deficient, Pik3caH1047R-mutant skin." (PMID 36765696, 2023). "Together, these data clearly show that the tumor suppressive function of Ripk4 is dependent on its kinase activity." (PMID 36765696, 2023). "While wildtype Ripk4 was able to rescue tumor suppression in these mice, mice reconstituted with kinase-dead Ripk4 developed SCC with the same latency and multiplicity as Ripk4 knock-out animals." (PMID 36765696, 2023). "The suggested implication of RIPK4 in tumorigenesis ranges from tumor-suppressor to tumor-promoter to involvement in metastasis." (PMID 37688617, 2023). "Several mechanisms have been described that mediate RIPK4’s tumor suppression such as the phosphorylation of PKP1 and STAT3." (PMID 36765696, 2023). "RIPK1 and RIPK3 are mainly involved in controlling and executing necroptosis in keratinocytes, while RIPK4 controls proliferation and differentiation of keratinocytes and thereby can act as a tumor suppressor in skin." (PMID 37688617, 2023). "In this study, we aimed to explore the prognostic value and tumor immunity relevance of RIPK4 in OC patients." (PMID 35310605, 2022). "We found that RIPK4 promotes tumour progression by promoting the invasion and metastasis of HCC and illustrated the close relationship between RIPK4 and the STAT3 pathway." (PMID 34222329, 2021). "The study confirmed that RIPK4 plays an important role in the development of HCC as a tumour suppressor gene and elaborated on the differential expression of RIPK4 in HCC tissues and normal tissues." (PMID 34222329, 2021). "Functional assays demonstrated that RIPK4-silenced OC cells exhibited suppressed tumour growth, migration, and invasion." (PMID 33855091, 2021). "Studies conducted in the recent past have reported that RIPK4 is involved in the processes of tumor initiation, development, and metastasis." (PMID 34124253, 2021). "Meanwhile, RIPK4 and SOBP mRNA expression was associated with the tumor pathological stage, which was consistent with their survival outcomes." (PMID 33742531, 2021). "We verified the differential expression of RIPK4 in HCC tumour tissues and normal tissues by PCR and Western blotting experiments." (PMID 34222329, 2021). "Consistent with RIPK4’s dual oncogenic and tumor-suppressive effects depending on the cellular context, β-TrCP also exerts dual functions in tumor development and progression." (PMID 32923402, 2020). "First, we explored whether RIPK4 regulates CXCR2 ligands using a cytokine array on tumor cell-conditioned media." (PMID 38744952, 2024). "However, despite the noticeable reduction in tumor burden at day 14 in mice with Ripk4 KD, the tumors that persisted continued to grow, leading to the mice eventually succumbing to the tumor burden in their lungs." (PMID 38744952, 2024).
tumor (continued). "Given that a hallmark feature of TNBC is an “immune-cold” microenvironment where lymphocyte infiltration into the tumor is limited, our data indicate that targeting RIPK4 may foster an increase abundance of lymphocytes at the tumor site." (PMID 38744952, 2024). "In essence, the distinct tumor growth patterns shed light on the survival advantage conferred by Ripk4 knockdown and underscores that RIPK4 may be mediating the rate-limiting step of cancer metastasis, seeding at the secondary site." (PMID 38744952, 2024). "Recent studies have shown that RIPK4 plays an important role in various cancers, exhibiting both oncogenic and tumor suppressive functions, depending on the cellular context." (PMID 38656555, 2024). "Similar to RIPK4, the role of NF-κB in different models of cancer as well as different tissues was shown to depend on the cellular context, as both, tumor suppressing and tumor promoting functions have been observed in different cancer models." (PMID 37688617, 2023). "Here, we describe an additional tumor suppressive feature of RIPK4 through upregulation of ELOVL4." (PMID 36765696, 2023). "Of note, forced expression of Irf6 could not rescue suppress tumor development in Ripk4-deficient, Pik3caH1047R-mutant skin, again indicating that the tumor suppressive function of Ripk4-Irf6 is dependent on Ripk4’s kinase activity." (PMID 36765696, 2023). "Therefore, we will further zoom in on the function of RIPK1 and -3 in keratinocyte cell death and the role of RIPK4 in epidermal differentiation and tumor suppression." (PMID 37688617, 2023). "To test whether the tumor suppressive function of Ripk4 depends on its kinase activity, we introduced these constructs into epidermis of compound mutant Ripk4fl/fl;Pik3caH1047R mice." (PMID 36765696, 2023). "Based on genetic evidence RIPK4 mainly acts as a tumor suppressor in the skin." (PMID 37688617, 2023). "Recently, several studies reported the roles of RIPK4 in tumor progression." (PMID 35310605, 2022). "In addition, RIPK4 plays a conflicting role as either a tumor suppressor or a tumor promoter in different tumor types." (PMID 35186499, 2022). "Meanwhile, RIPK4 is essential for epidermal differentiation, and during cancer progression, poorly differentiated cancers appear to present a higher degree of cell migration, thus promoting the dissemination of cells from the tumor mass." (PMID 35186499, 2022). "Our findings revealed that the dysregulation of RIPK4 may influence the function of tumor microenvironment." (PMID 35310605, 2022). "Our study confirmed that the expression of RIPK4 in HCC tumour tissues is significantly lower than that in normal liver tissue according to public data sets, and we applied tissue sample data collected from patient samples from our study to verify the expression of RIPK4 in HCC tumour tissues." (PMID 34222329, 2021). "Similarly, RIPK4 has also been identified as a putative and novel tumor suppressor in human hepatocarcinogenesis." (PMID 32923402, 2020). "The role of RIPK4 as a tumor suppressor involved in HCC development might relate to NF-κB signaling." (PMID 32923402, 2020). "In addition, the function of RIPK4 in carcinogenesis is probably tissue-specific, since RIPK4 can play a dual role as both a tumor promoter and a tumor suppressor in different tumor types." (PMID 32923402, 2020). "The current controversy concerning the potential role of RIPK4 in carcinogenesis indicates that RIPK4 may have a context-specific function in carcinogenesis and/or different signal transduction mechanisms in different tumor types." (PMID 32923402, 2020). "RIPK4 promoted Wnt signaling, implying that RIPK4 overexpression might be involved in the development of certain tumor types." (PMID 32923402, 2020). "Besides the RIPK4 level, the impact value of a patients’ age, patients’ gender, tumour size, tumour multiplicity, tumour grade and stage were also been tested in the univariate analysis for OS." (PMID 29867225, 2018).